NPM1 (nucleophosmin 1)
Diseases named in the same sentence as NPM1 in open-access papers (continued):
Sharing a sentence is not in itself a finding about the gene and the disease.
pancreatic cancer (12 papers, 2015 to 2026). "Data mining of the TCGA_PDAC dataset revealed that NPM1 OE in pancreatic cancer was associated with unfavorable clinical outcomes." (PMID 41114465, 2026). "First, we found that NPM1 was up-regulated in pancreatic tumor specimens and associated with the prognosis." (PMID 26068981, 2015). "Functional assays demonstrated that NPM1 promotes pancreatic cancer cell proliferation, as NPM1 KD significantly inhibited cell growth and foci formation." (PMID 41114465, 2026). "The consequent stabilization of NPM1 enhances ribosome biogenesis, driving pancreatic cancer progression and gemcitabine resistance." (PMID 41114465, 2026). "Significantly, combining gemcitabine with NPM1 inhibitor NSC348884 synergistically suppresses CSN6‐high pancreatic cancer xenografts." (PMID 41114465, 2026). "Phosphoproteomic analyses following 51-106 treatment revealed that nucleophosmin (NPM1)T199 phosphorylation is decreased upon MAP3K1 inhibition and is associated with cell cycle regulation in pancreatic cancer cells." (PMID 40363807, 2025). "NPM1 bound directly to the FBP1 promoter region to suppress the expression of FBP1 in pancreatic cancer cells." (PMID 30429463, 2018). "NPM1 bound directly to the FBP1 promoter region to suppress the expression of FBP1 in pancreatic cancer." (PMID 29556139, 2018). "Restoring FBP1 in pancreatic cancer cells reversed the NPM1-induced dysfunction of glucose metabolism." (PMID 29556139, 2018). "Yi Zhu and his group identified that the nucleophosmin (NPM1) which can promote Warburg effect in vitro was found up-regulated in pancreatic cancers, and indicated a poor prognosis link in their study." (PMID 28076853, 2017). "To study this possibility, we obtained four pancreatic cancer cell lines (Panc-1, Bxpc-3, Aspc-1, Sw1990) and tested the mRNA and protein levels of NPM1 in each." (PMID 26068981, 2015). "Knock-downs of NPM1 in pancreatic cancer cell lines likely impair glucose uptake and lactate production." (PMID 26068981, 2015). "To investigate the correlation between NPM1 and the prognosis of pancreatic cancer, we analyzed the IHC staining results combined with postoperative fellow-up data." (PMID 26068981, 2015). "We had showed that the staining intensity of NPM1 correlates with the prognosis of pancreatic cancer." (PMID 26068981, 2015). "In sum, NPM1 promotes aerobic glycolysis and tumor progression in patients with pancreatic cancer by inhibiting FBP1." (PMID 26068981, 2015). "NPM1 was also found up-regulated in pancreatic cancer, and indicated a poor prognosis in their study." (PMID 26413751, 2015). "However, the regulatory role and underlying mechanisms of NPM1 in pancreatic cancer are unknown." (PMID 26068981, 2015). "To further demonstrate that FBP1 is a critical target gene involved in the NPM1-induced phenotypes of pancreatic cancer cells, we over-expressed FBP1 and NPM1 in the Bxpc-3 cell lines, and effective restoration of FBP1 expression in Bxpc3 cells was confirmed by qRT-PCR." (PMID 26068981, 2015). "In this study we found a novel role for NPM1 in metabolic regulation in pancreatic cancer." (PMID 26068981, 2015). "However, the specimens we used were all from patients with a resectable pancreatic cancer, and we also didn't know if the high expression of NPM1 was a final result of therapy." (PMID 26068981, 2015). "Fourth, restore the FBP1 in pancreatic cancer cells could reverse the NPM1-induced glucose metabolism dysfunction." (PMID 26068981, 2015). "Therefore, we hypothesized that NPM1 can promote the progression of pancreatic cancer (via enhancing cancer cell growth)." (PMID 26068981, 2015). "However, the relationship between NPM1 and pancreatic cancer remains unclear." (PMID 26068981, 2015).
liver cancer (11 papers, 2015 to 2026). An epithelial or non-epithelial malignant neoplasm that arises from the liver. "A previous study demonstrated that NPM1 is expressed weakly in normal hepatocytes and is highly expressed in liver cancer cells with a clear correlation between enhanced NPM1 expression and increased tumor grade and consequently poor prognosis." (PMID 25779011, 2015). "The polyclonal anti-NPM1 antibody was used as the primary antibody to detect the expression of NPM1 in both liver cancer and normal tissues." (PMID 25779011, 2015). "In the present study, the expression profile of NPM1 in liver cancer and normal liver tissues was examined by immunohistochemistry with tissue array slides." (PMID 25779011, 2015). "In the present study, we also found that NPM1 expression was markedly increased in liver cancer tissues." (PMID 25779011, 2015). "The study showed that liver cancer patients with lower levels of NPM1 have a better prognosis." (PMID 38097352, 2023). "Indeed, the patients of liver cancer with lower expression levels of LETN or NPM1 had better prognosis." (PMID 33432115, 2021). "In order to test dynamic changes in anti-NPM1 autoantibodies during malignant transformation from chronic liver diseases to liver cancer, the sera from three HCC cases with serial bleeding serum samples were available in our laboratory, and were tested in the present study." (PMID 25779011, 2015). "NPM1 can promote cellular/tumor growth via novel NPM-BAX death evasion pathways in liver cancer." (PMID 26068981, 2015). "Given that NPM1 is already a therapeutic target in hematopoietic cancers, our findings suggest that targeting NPM1 could also benefit patients with WNT-driven solid tumors, such as KRAS-mutant CRC and hepatic cancers, which remain challenging to treat." (PMID 41413654, 2026). "Notably, NPM1 depletion suppressed Kras-mutant WNT-driven CRC and restricted WNT-driven liver cancer, both high-mortality diseases with limited treatment options." (PMID 41413654, 2026). "Subsequently, NPM1 translocated from the nucleus to the cytoplasm and plasma, where it interacted with ELMO1, activated small GTPases (Rac1), and ultimately triggered actin polymerisation and liver cancer cell migration." (PMID 37251542, 2023).
lung adenocarcinoma (11 papers, 2013 to 2026). A carcinoma that arises from the lung and is characterized by the presence of malignant glandular epithelial cells. "In lung adenocarcinoma, increased NPM1 expression is associated with poor patient prognosis." (PMID 40705480, 2025). "In lung adenocarcinoma, NPM1 is also involved in immune infiltration and its expression is closely related to the presence of a variety of immune cells." (PMID 34899858, 2021). "qRT-PCR results showed that the expression level of NPM1 mRNA was significantly increased in human lung adenocarcinoma cell lines compared with normal human lung epithelial cells." (PMID 34335635, 2021). "NPM1 is overexpressed in several types of tumors and has been evidenced to promote the occurrence and progression of tumors, currently it could be used as a prognostic biomarker involved in immune infiltration of lung adenocarcinoma (LUAD)." (PMID 36277962, 2022). "However, there are few studies on the comprehensive analysis of NPM1 in lung adenocarcinoma (LUAD)." (PMID 34335635, 2021). "In lung adenocarcinoma (LUAD), nucleophosmin 1 (NPM1) impacts B and NK cell survival through glycolytic metabolism and YTHDF2-mediated m6A methylation." (PMID 39033180, 2024). "Five genes were flagged as mutant in all 8 lung adenocarcinoma samples namely RET, APC, FGFR3, NPM1 and PDGFRA when the least stringent QBVD threshold was applied (QBVDi = 71)." (PMID 23922754, 2013).
acute lymphoblastic leukemia (10 papers, 2018 to 2025). Leukemia with an acute onset, characterized by the presence of lymphoblasts in the bone marrow and the peripheral blood. "AML or acute lymphoblastic leukemia (ALL) with KMT2A gene rearrangement (r), AML with NPM1 mutation (NPM1mut) and few other subtypes are dependent on downstream MEIS/HOXA activation for leukemogenesis and are amenable to menin inhibition." (PMID 41310838, 2025). "KMT2A mutations arise in 80% of acute lymphoblastic leukemia (ALL) and, together with mutations related to NPM1, in 30% of acute myeloid, lymphoid or mixed phenotype leukemia (AML)." (PMID 37816719, 2023).
glioblastoma (10 papers, 2007 to 2024). The most malignant astrocytic tumor (WHO grade IV). "In summary, NPM1 was significantly upregulated in glioblastomas and displayed a more generalized nuclear staining compared with the more exclusive nucleolar staining seen in normal cells." (PMID 26559910, 2015). "A third possibility is that glioblastoma cells and NSCs are exposed to more cellular damage, including nucleolar stress, creating a shift in NPM1 ́s localization more towards the nucleoplasm." (PMID 26559910, 2015). "NPM1+ cells were detected in low-grade astrocytic gliomas and in adjacent near-normal brain areas, but the staining intensity was considerably weaker than in glioblastomas." (PMID 26559910, 2015). "Besides elevated levels of the protein resulting in a nucleolar spillover, it is possible that the chromatin landscape in glioblastoma cells and NSCs may allow for an increase in nucleoplasmic NPM1." (PMID 26559910, 2015). "The 67 NPM1/HIF‐1α‐dependent gene signature was highly expressed in three cancer types with elevated NPM1 expression, namely lymphoid neoplasm diffuse large B‐cell lymphoma (DLBC), glioblastoma multiforme (GBM), and thymoma (THYM)." (PMID 34388291, 2021).
myeloid leukemia (10 papers, 2013 to 2025). A clonal proliferation of myeloid cells and their precursors in the bone marrow, peripheral blood, and spleen. "Interestingly, NPM1 variants frequently co-occur with DNMT3A in the pathogenesis of myeloid leukemias." (PMID 39626264, 2025). "However, mice genetically engineered to express only one wild-type NPM1 allele display a higher susceptibility to hematological malignancies, including myeloid leukemia, indicating that loss of NPM1 function is a mechanism of pathogenicity." (PMID 27525194, 2015). "As2O3 is used to degrades mutated NPM1, which eventually leads to AML cell apoptosis, thereby treating myeloid leukemia patients." (PMID 33842551, 2021). "CN-AML was significantly found in AML patients aged ≥ 40 years, and mutation of NPM1 and CEBPA genes were significantly exhibited in this group, therefore these driven gene mutations were associated with myeloid leukemia development in the middle aged and the older patients." (PMID 30729065, 2019). "Notably, FLT3 and NPM1, common driver variants associated with the development of myeloid leukemia, are virtually non-existent in CH, suggesting that the acquisition of these variants likely occurs later in the pathogenesis of AML and is strongly linked to leukemogenesis." (PMID 39626264, 2025).
myeloid sarcoma (10 papers, 2016 to 2026). A tumor mass composed of myeloblasts or immature myeloid cells. "Similar dramatic responses have been also reported in NPM1-mutated myeloid sarcoma." (PMID 33879827, 2021). "Chromosome deletion, KMT2A rearrangement, NPM1 mutation and RUNX1-RUNX1T1 rearrangement can be detected in more than half of myeloid sarcoma cases." (PMID 41384108, 2025). "One patient with NRAS, MPL positivity, FLT3/NPM1 WT had received 2 courses of high-dose cytarabine inductions with residual BM blast burden 80% and dural myeloid sarcoma." (PMID 35039473, 2022). "Some case reports found FLT3-ITD and NPM1 variations in myeloid sarcomas with high frequencies of 15 and 14.4 %, respectively." (PMID 27724883, 2016). "NPM1 immunohistochemistry revealed aberrant cytoplasmic signal (original magnification 500×, inset original magnification 1000×), confirming the diagnosis of NPM1‐mutant myeloid sarcoma." (PMID 35846035, 2022). "In haematological centers performing BM biopsy at presentation, demonstration by IHC of cytoplasmic NPM1 may serve as surrogate to molecular techniques in case of dry tap or myeloid sarcoma (case 2)." (PMID 33879827, 2021).
chronic myelomonocytic leukemia (9 papers, 2020 to 2025). A myelodysplastic/myeloproliferative neoplasm which is characterized by persistent monocytosis, absence of a Philadelphia chromosome and BCR/ABL fusion gene, fewer than 20 percent blasts in the bone marrow and blood, myelodysplasia, and absence of PDGFRA or PDGFRB rearrangement. "This brief communication describes the case of a patient diagnosed with chronic myelomonocytic leukemia with NPM1 mutation and briefly review the literature to highlight the uncertainty about how to classify this condition." (PMID 39349391, 2025). "The mutation rates for DNMT3A and TET2 in either gene or both were as high as 92.9% in angioimmunoblastic T cell lymphoma, 80% in chronic myelomonocytic leukemia, 58.4% AML with mutated NPM1 and 57.1% in peripheral T cell lymphoma." (PMID 34039392, 2021). "Very recently, NPM1-mutated MDS and chronic myelomonocytic leukemia CMML cases represent NPM1-mutated AML diagnosed at an early stage and the NPM1 mutant defines AML irrespective of the blast count." (PMID 38255885, 2024).
ovarian cancer (9 papers, 2007 to 2025). A primary or metastatic malignant neoplasm involving the ovary. "An overexpression of NPM1 is linked to unsuitable outcomes for women with ovarian cancer." (PMID 40643517, 2025). "Interestingly, we have previously demonstrated that upregulation of ribosome biogenesis including NPM1 by the oncogenic mir196a2 variant was one of key mechanisms involved in the malignant transition from endometriosis to the related ovarian cancer." (PMID 33667269, 2021). "It has been shown that NPM1 is overexpressed in drug-resistant ovarian cancer cells using an in-depth proteomic mass spectrometry study." (PMID 31557908, 2019). "The interaction between APE1 and nucleophosmin 1 (NPM1) has been extensively examined in ovarian cancer, as the levels of the two proteins were positively associated with tumor aggressiveness, malignant phenotype, lymph node metastasis, and poor chemosensitivity." (PMID 37508559, 2023). "In addition, in high-grade ovarian serous cancer, a poorer patient outcome was associated with a significant overexpression of nuclear NPM1 and in transformed ovarian cancer cells, elevated levels of NPM1 were reported." (PMID 31557908, 2019). "Accordingly, a correlation between increased NPM1 expression levels and tumour progression has been established in a wide set of solid tumours of diverse histological origins such as in gastric-, colon, kidney or ovary cancers." (PMID 24796332, 2014).
non-Hodgkin lymphoma (8 papers, 2018 to 2025). Distinct from Hodgkin lymphoma both morphologically and biologically, non-Hodgkin lymphoma (NHL) is characterized by the absence of Reed-Sternberg cells, can occur at any age, and usually presents as a localized or generalized lymphadenopathy associated with fever and weight loss. "Another notable example is nucleophosmin (NPM-1), a key component of the nucleolus, which is also part of the NPM-ALK fusion product in non-Hodgkin’s lymphoma." (PMID 29416553, 2018). "Several therapeutic strategies have been explored to target aberrant cytosolic localization of mutant NPM1 in AML including inhibitors of nuclear export such as leptomycin B or selinexor, which has interestingly shown clinical activity in a phase I trial in refractory non-Hodgkin lymphoma." (PMID 34885010, 2021).
Ewing sarcoma (7 papers, 2018 to 2024). A small round cell tumor that lacks morphologic, immunohistochemical, and electron microscopic evidence of neuroectodermal differentiation. "Researchers found that Aurora kinase A (AURKA) induced apoptosis and ferroptosis in Ewing’s sarcoma cells by inhibiting the NPM1/YAP1 axis, suggesting that AURKA may be a potential target for Ewing’s sarcoma." (PMID 39314848, 2024). "In addition, studies by Huimou Chen and others have reported that AURKA induces apoptosis and ferroptosis in Ewing’s sarcoma cells through the NPM1/YAP1 axis." (PMID 38673957, 2024). "NSC348884, an NPM1 inhibitor that disrupts oligomer formation and induces apoptosis, has demonstrated antitumor activity in CRC and Ewing sarcoma cells in vitro." (PMID 36428674, 2022). "Furthermore, NSC348884, an NPM1 inhibitor that disrupts oligomer formation and induces apoptosis, has demonstrated antitumor activity in CRC and Ewing sarcoma cells in vitro." (PMID 36428674, 2022).
multiple myeloma (6 papers, 2012 to 2024). "It is speculated that myeloma cells may proliferate more dependently on TC11-associated molecules such as NPM1." (PMID 25617756, 2015). "In AML with mutations in NPM1 (encoding nucleophosmin), I-BET151 abrogates the HOX-independent transcription program, and represses the MYC-dependent program in myeloma, leading to strong antiproliferative effect in vitro and in vivo." (PMID 30906568, 2019). "As a next step to clarify exact signaling pathway after binding of TC11 to NPM1, we are trying to knock-down of NPM1 gene in myeloma cells and examine the effects of TC11 on oligomerization and phosphorylation of NPM1 in myeloma cells." (PMID 25617756, 2015). "Consequently, TC11-treated myeloma cells fall into mitotic catastrophe because NPM1 and tubulin families are key molecules for cell division." (PMID 25617756, 2015). "Therefore, it is speculated that the principal actions of TC11 on myeloma cells are centrosomal disruption and abnormal microtubule assembly by binding to NPM1 and α-tubulin, respectively." (PMID 25617756, 2015). "Therefore, TC11 might affect myeloma cells by blocking the oligomerization of NPM1 and inhibiting its various functions." (PMID 25617756, 2015). "To clarify the mechanism of TC11’s anti-myeloma effect, we investigated the effects of TC11 on NPM1, since we have found that NPM1 is one of the binding targets of TC11 by an mRNA display (i.e., the IVV method)." (PMID 25617756, 2015). "We also examined nucleophosmin-1 (NPM1) as a molecule that binds directly to phthalimide, and the results raised the possibility that α-tubulin is involved in the anti-myeloma effect of TC11." (PMID 25617756, 2015).
neuroblastoma (6 papers, 2017 to 2023). Neuroblastoma (NB) is the most common solid, extracranial childhood tumor. "Here we found that neurospheres derived from neuroblastoma stem-like cells showed a homogeneous staining for several key nucleolar proteins, such as Nucleolin, Nucleophosmin-1, Glypican-2 and PES-1." (PMID 32737364, 2020). "Our data show that NPM1 interacts with DOT1L in the neuroblastoma N2a cell line." (PMID 37759327, 2023). "In this work, we addressed a potential synergy between mouse NPM1 and DOT1L, with a specific focus on heterochromatin organization around nucleoli in the neuroblastoma N2a cell line." (PMID 37759327, 2023).
acute myelomonocytic leukemia (5 papers, 2014 to 2025). "UF1570 (BM) was diagnosed with acute myelomonocytic leukemia NPM1+, and the predicted subtype was AML with mutated NPM1 (0.885)." (PMID 39711573, 2024). "Patient ALMA_10_BM (60 + years, male; coverage 12.16x), clinically presenting acute myelomonocytic leukemia with NPM1 mutation, was predicted as AML with mutated NPM1, confirmed by genomic detection of a NPM1 pathogenic frameshift (c.860_863dupTCTG; p.Trp288fs)." (PMID 40730747, 2025).
anemia (5 papers, 2019 to 2025). A reduction in the number of red blood cells, the amount of hemoglobin, and/or the volume of packed red blood cells. "AML with NPM1 mutation commonly occurs in cytogenetically normal AML and is clinically characterized by elevated white blood cell counts, increased immature cells, anemia, and thrombocytopenia." (PMID 39432585, 2024).